MTOR (mechanistic target of rapamycin kinase)
Diseases named in the same sentence as MTOR in open-access papers (continued):
Sharing a sentence is not in itself a finding about the gene and the disease.
emphysema (continued). "Similarly, inhibition of the mTOR pathway with the AMP-activated protein kinase (AMPK) activator metformin was shown to decrease the development of senescence, SASP secretion, and emphysema in the elastase-induced murine model of emphysema." (PMID 35912114, 2022). "Furthermore, rapamycin (mTOR inhibitor) successfully decreases mTOR activity and induction of cellular senescence in COPD-derived epithelial cells and mouse models of emphysema." (PMID 34685744, 2021).
gastric tumors (19 papers, 2010 to 2025). "Our CEA424-SV40 T antigen gastric tumors and derived tumor cell lines highly express phosphorylated mTOR downstream substrates S6K and 4EBP1, indicating high mTOR activity." (PMID 32373532, 2020). "Rapamycin also up-regulates CD133 expression via inhibition of mTOR signaling in colorectal and gastric tumor cells." (PMID 27780926, 2016). "Blockade of mTOR signaling with rapamycin impaired GLI2A-driven gastric tumor growth and affected both proliferation and differentiation." (PMID 26859571, 2016). "Targeting PI3K/AKT/mTOR canbe used as a potent antineoplastic therapeutic method via the suppression of the pathway using flavonoids, which permits the inactivation of mTOR, the induction of autophagy, and the gastric tumor cell death by stopping them in the M/G2 cycle checkpoint." (PMID 34947835, 2021). "Another study has demonstrated that MET-induced apoptosis in human gastric tumor cells (HGC27, SGC7901) by inhibiting the PI3k/Akt/mammalian target of rapamycin (mTOR) signal pathway, reduced the number of M2-type macrophages and increased the M1-type." (PMID 37509632, 2023). "Western blot and immunostaining showed that both the cell lines and the tumor tissue highly express the downstream target of mTOR, indicating that in the CEA424-SV40 TAg gastric tumor and the cell lines mTOR pathway is highly active." (PMID 32373532, 2020). "Collectively, these results suggest that the oncogenic role of c-Myc is mediated through the activation of AKT/mTOR signaling and blocking AKT/mTOR signaling may be helpful to inhibit or postpone the onset of gastric tumors." (PMID 33259779, 2021). "Our results showed that expression levels of AKT and mTOR are significantly increased in c-Myc transgenic mice, and inhibition of AKT and mTOR can significantly decrease cell proliferation in AGS cells overexpressing c-Myc and inhibit or postpone the onset of gastric tumors in vivo." (PMID 33259779, 2021). "These dual PI3K/mTOR inhibitors have been shown to enhance 5-FU cytotoxicity both in vitro and in vivo, especially in PI3KCA mutant gastric tumor cells which are thought to be secondary to cellular heterogeneity in regard to sensitivity to PI3K and mTOR inhibition." (PMID 26267324, 2015). "Therefore, the mechanism by which inactivation (no phosphorylation) of the AKT (Ser473)/mTOR (Ser2448) pathway affects TOB1-induced autophagy in gastric tumor cells needs to be further explored." (PMID 35186488, 2022).
hypertriglyceridemia (19 papers, 2006 to 2025). A laboratory test result indicating elevated triglyceride concentration in the blood. "However, the management of plasma triglycerides may be particularly difficult in patients who receive the mTOR inhibitors sirolimus or everolimus, as these agents are clearly associated with marked hypertriglyceridemia." (PMID 29411291, 2018). "However, despite these antitumor effects, mTOR inhibitors are rarely given right after solid organ transplantation, because they have been associated with the increased incidence of wound healing complications and severe side effects, including peripheral edema and hypertriglyceridemia." (PMID 41322122, 2025). "However, the inhibition of mTOR, despite decreasing lipid uptake and storage, results in hypertriglyceridemia, which is why mTOR and PPARγ also modulate lipid metabolism in the plasma." (PMID 41287647, 2025). "In patients with mTOR-inhibitor-related severe hypertriglyceridaemia, fenofibrate should be considered the drug of first choice; if LDL-C concentrations are elevated too, a statin therapy could be added under strict surveillance for potential drug-related myopathy." (PMID 36009482, 2022). "Therefore, to examine whether hepatic mTOR/S6K activation leads to hypertriglyceridemia, we expressed Rheb, which reportedly activates mTORC1 (refs 9, 10, 31)." (PMID 26268630, 2015). "He only developed modest hypertriglyceridemia (known complication of mTOR inhibitor therapy), that is not sufficient itself to justify the clinical presentation of acute necrotizing pancreatitis." (PMID 27793122, 2016).
Hypoglycemia (19 papers, 2017 to 2026). A decreased concentration of glucose in the blood. "Defects in the PI3K/AKT/mTOR signaling pathway are considered among the genetic causes of recurrent hypoglycemia in childhood and hypoglycaemia is commonly observed in patients affected by overgrowth syndromes associated with mutations in the PIK3CA gene." (PMID 40354343, 2025). "In such cases, diazoxide, somatostatin analogs, and the mTOR inhibitor everolimus have been effective in controlling hypoglycemia." (PMID 37601782, 2023). "Sirolimus treatment, resulting in mTOR inhibition, appeared to be effective in controlling the persistent hypoglycemia in two cases." (PMID 32157856, 2020). "In our cases, we decided to give sirolimus to improve hypoglycemia in a patient with AKT2 mutation and another patient with PTHS as sirolimus will inhibit mTOR, the next downstream step in PTEN/AKT signalling." (PMID 32157856, 2020). "A novel finding in this study is that treatment with α-lipoic acid in the Akt-dependent phosphorylation site on mTOR is a strong steatohepatitis protector, leading to enhanced glucose and insulin tolerance and finally hypoglycemia, which was also noticed in our previously published data." (PMID 38794739, 2024). "Mechanistically, fasting inhibited mTOR activity by inducing hypoglycemia, which acted in two ways." (PMID 34732698, 2021). "Sirolimus treatment, through mTOR inhibition, appeared to be effectively controlling the peristent hypoglycemia and may be a life-saving therapy in this NkHH due to AKT2 and PTEN mutations." (PMID 32157856, 2020). "In addition, somatostatin analogues (e.g., octreotide and lanreotide) can suppress hormone release, and newer agents such as everolimus (an mTOR inhibitor) and pasireotide (a multireceptor somatostatin analogue) have shown promise in controlling refractory hypoglycemia." (PMID 40124204, 2025). "In addition, everolimus, an mTOR inhibitor, has been reported effective in controlling insulin-induced hypoglycemia in malignant insulinomas refractory to somatostatin analogues, and could be considered in this patient." (PMID 36835815, 2023). "Recently, it has been demonstrated in models of hypoglycemia or aglycemia that activities of microglia, such as process motility and damage sensing functions, are maintained by alternative metabolic pathways such as glutaminolysis, which depend on mammalian target of rapamycin (mTOR) activation." (PMID 33262692, 2020). "Hence, both hypoglycemia and uncontrolled cell proliferation in various tissues may be controlled with mTOR inhibition." (PMID 32157856, 2020). "However, it has been shown that phenformin is, with other biguanides, an authentic tumor disruptor, not only by the production of hypoglycemia due to caloric restriction through AMP-activated protein kinase with energy detection (AMPK) but also as a blocker of the mTOR regulatory complex." (PMID 31284513, 2019). "Here, in vitiligo cells, the lack of coordination between AMPK and mTOR/S6 signaling, the two most important metabolic signaling pathways, reflects the improper perception of hypoglycemia." (PMID 40277891, 2025).
pituitary adenomas (19 papers, 2011 to 2025). "Regulation of FANCD2 by the mTOR pathway, a molecular pathway known to contribute to cancer cell resistance to DNA damage also in pituitary adenoma, increases tumor cell survival." (PMID 40415137, 2025). "The PI3K/AKT/mTOR pathway has been shown to be overexpressed in both hormonally active and inactive pituitary adenomas compared to a normal pituitary gland." (PMID 37446128, 2023). "The research conducted on GH3 and GH4C1 rat pituitary adenoma cell lines showed that IGF1 improves somatotroph cell viability through the PI3K/AKT/mTOR pathway and the inhibitory effect of IGF1 on GH secretion via this pathway." (PMID 37446128, 2023). "mTOR mRNA expressions significantly modulated in invasive pituitary adenoma tissues were compared with those in noninvasive pituitary adenoma tissues." (PMID 33023145, 2020). "Several studies have shown that the activation of PI3K/Akt/mTOR pathway is also a feature of pituitary adenomas, including NFPAs." (PMID 27992366, 2017). "Pituitary adenomas from TRβPV/PV mice show increased phosphorylation of Akt (Ser473), mTOR and S6 on western blotting, and PI3K/Akt inhibition decreases pituitary tumor mass and increases apoptosis." (PMID 26793165, 2015). "Pituitary adenomas have also been reported to have increased levels of mTOR activation, as measured by phosphorylation of downstream S6, with GHomas showing the most marked elevation of mTOR activity." (PMID 26793165, 2015). "Our data suggest mTOR promotes pituitary adenoma growth and radioresistance, indicating a possible therapeutic role for mTOR inhibitors in the clinical management of pituitary tumors." (PMID 21427787, 2011). "Basal mTOR functionally contributed toward the cellular growth of pituitary adenoma cells as pharmacological inhibition of mTOR limited cellular proliferation." (PMID 21427787, 2011). "In the present study, both rapamycin and RAD001 attenuated mTOR activation and increased acute G1 growth arrest in pituitary adenoma cell lines." (PMID 21427787, 2011). "In a study involving 53 PAs, growth hormone-secreting pituitary adenomas (GH-PAs) (10/14, 71%) and non-functional pituitary adenomas (NFPAs) (11/33, 33%) showed a significant association with the mTOR pathway, compared to the control group (1/5, 20%)." (PMID 39736867, 2024). "It has been shown that mTOR inhibitors are effective in pituitary adenomas." (PMID 37446128, 2023). "DEPTOR, an important modulator of mTOR, is downregulated in pituitary adenomas." (PMID 34221237, 2021). "Collectively, these results suggest that BT may inhibit the mTOR pathway in pituitary adenomas." (PMID 34221237, 2021). "In pituitary adenoma, Zhang reported that CCL17 chemokine secreted from M2 macrophages promotes tumor invasion via the mTOR/Akt473 pathway." (PMID 38576043, 2024). "Analysis of 53 pituitary samples, including GH-PAs, NFPAs, and ACTH-secreting pituitary adenomas (ACTH-PAs), revealed elevated mTOR activity (estimated by the pS6/eIF4E ratio)." (PMID 39736867, 2024). "The combination of dual PI3K/mTOR inhibition and temozolomide has been demonstrated to synergistically inhibit tumor growth and reduce GH/PRL levels in pituitary adenoma cell lines and in a mouse GH3 tumor model." (PMID 32012988, 2020). "Clinically achievable concentration of the mTOR inhibitors, rapamycin and RAD001, reduced cellular proliferation and radiosenstized pituitary adenoma cells, at least in part, by inducing G1 growth arrest." (PMID 21427787, 2011). "Everolimus (an mTOR inhibitor) and bevacizumab (a monoclonal antibody against VEGF) have been the main target therapies that have been reported for the treatment of aggressive pituitary adenomas/PitNEts." (PMID 36658300, 2023).
pituitary adenomas (continued). "Given the important role of the PI3K/Akt/mTOR and Raf/Mek/ERK pathways in pituitary tumor pathogenesis, a number of agents targeting these pathways have been investigated in the treatment of pituitary adenomas; however, most evidence of activity comes from preclinical studies." (PMID 32012988, 2020). "However, some reports showed that the expressions of phosphorylated/total mTOR or p70S6K were not different between pituitary adenomas and controls." (PMID 27992366, 2017). "The dual mTOR/PI3K inhibitor NVP-BEZ235 reduces cell proliferation and promotes cell death in rat non-functioning pituitary adenomas in vitro and in vivo, in growth hormone-secreting GH3 cell lines in vitro, and in primary cell cultures of human prolactinomas." (PMID 32012988, 2020). "However, mTOR activity appeared to be independent of PI3K/Akt signaling in pituitary adenoma cells on primary culture, and mTOR activity was not related to clinicopathological characteristics in the sample of 53 pituitary adenomas." (PMID 26793165, 2015).
Atrophy (18 papers, 2010 to 2025). Any weakening or degeneration, especially through lack of use. "Muscle atrophy was caused not only by the disruption of the IGF1/PI3K/Akt/mTOR pathway signaling but also by the observed decrease in myogenin expression in aged fish, which also contributes to muscle degeneration." (PMID 38892357, 2024). "For musculoskeletal diseases, isoliquiritigenin has been shown to mitigate dexamethasone-induced muscle atrophy by increasing myotube diameters and decreasing expression of Atrogin-1 and MuRF-1 through the Akt/mTOR signaling pathway." (PMID 40722900, 2025). "Here we present evidence that in MAFbx-induced atrophy thedegradation of eIF3f suppresses S6K1 activation by mTOR, whereas an eIF3f mutantinsensitive to MAFbx polyubiquitination maintained persistent phosphorylation ofS6K1 and rpS6." (PMID 20126553, 2010). "In the present work, we show in MAFbx-induced atrophy that the decreased activity ofmTORC1 is correlated with the degradation of eIF3f and inversely mTOR and itsdownstream targets S6K1 and 4E-BP1 via eIF3f control muscle size." (PMID 20126553, 2010). "To test if improved cell metabolism by sustained activation of the insulin/mTOR pathway prolongs cone survival in the sodium iodate induced model of RPE atrophy, we constitutively activated the pathway in cones at two separate junction points downstream of the insulin receptor." (PMID 26883199, 2016). "In SBMA, polyglutamine expansion in the AR may result in aberrant and sustained activation of mTOR that in turn can contribute to muscle atrophy during disease progression." (PMID 26971100, 2016). "Our observation that immobilization induces the activation of mTOR signaling was unexpected, but it was not entirely surprising because recent studies have shown that denervation of the sciatic nerve, which induces neurogenic atrophy, also results in the activation of mTOR signaling." (PMID 26092121, 2015). "Because Akt and SGK can regulate the pro-growth mTOR pathway, we also examined whether this pathway was dysregulated in our models of atrophy." (PMID 24504412, 2014). "In the denervation-induced muscle atrophy model, CIE treatment led to a dose-dependent decrease in apoptosis-related factors (especially cleaved caspase-3) and mitigated the Akt/mTOR signaling pathway." (PMID 40647221, 2025). "Previously, NPN_1 was shown to induce expression of genes involved in myogenesis (mTOR and MYF5) in a murine model of atrophy as well as p-S6 expression in vitro." (PMID 36839344, 2023). "In Imo‐induced muscle atrophy, circTmeff1 knockdown enhanced muscle mass, reduced expression of Atrogin‐1 and MuRF‐1, increased CSA of myofibers, and reactivated AKT/FOXO3A/mTOR signaling pathway in this muscle atrophy model." (PMID 37088818, 2023). "Muscle atrophy induced by the TGF-β member myostatin involves Smad2/3 signaling that activates MAFbx expression and downregulates mTOR signaling." (PMID 36402791, 2022). "We then examined the effects of Dexa and obestatin on protein levels and phosphorylation status of AMPK and Akt, the upstream activator of mTOR, and mTOR downstream effectors S6 and 4E‐BP1, in the mouse GC‐induced atrophy model." (PMID 33687156, 2021). "RSV has also been shown to upregulate the phosphorylation of protein kinase B (Akt), p70 ribosomal S6 protein kinase (p70S6K), mammalian target of rapamycin (mTOR), and eukaryotic translation initiation factor 4E- (eIF4E-) binding protein 1 (4E-BP1) in TNF-α-induced atrophy." (PMID 38020198, 2023).
brain cancer (18 papers, 2013 to 2025). A primary or metastatic malignant neoplasm affecting the brain. "Recent advances in the development of brain-penetrant pan- and selective PI3K and mTOR inhibitors provide the field with potent new weapons against these historically lethal pediatric brain cancers." (PMID 40386392, 2025). "It has been found that taxifolin have effect of treatment on primary malignant brain tumor by inhibited mTOR/PI3K, promoted autophagy and suppressed lipid synthesis in GBM." (PMID 36838870, 2023). "Ongoing research aims to optimize mTOR-targeted therapies to achieve better clinical outcomes in patients with this deadliest brain cancer." (PMID 37834408, 2023). "First-generation inhibitors of mTOR have been approved for the treatment of breast, pancreatic, renal, and some brain cancers." (PMID 34397726, 2021). "Importantly, IAPs expression in the ERK-MAPKi resistance group including 3 types of brain cancers were associated with sensitivity to EGFR inhibitor, PI3K/MTOR inhibitor and WNT signaling inhibitors." (PMID 31964418, 2020). "The PI3K/AKT/MTOR signaling pathway also plays a key role in cancer biology, first generation MTOR inhibitors were approved for treatment of multiple cancer types, including renal, breast and some brain cancers." (PMID 31597567, 2019). "In the context of brain cancer related radiosensitizer research, chemoradiation investigations were prominent in the 20th century, while articles from the 21st century highlight nanoparticles, ATM inhibitors, mTOR inhibitors and inhibition of PARP." (PMID 40667051, 2025). "In addition, plumbagin is known to prevent brain cancer progression and metastasis by downregulating PI3K/Akt/mTOR signaling and suppressing MMP2/9 activation." (PMID 36307808, 2022). "For example, while pediatric brain cancers are largely driven by epigenetic dysregulation and micro-environmental influences exert a greater effect on adult brain cancers, common molecular drivers between the two include MYCN, NOTCH, PI3K/AKT/MAPK/mTOR, WNT/−catenin, and SHH." (PMID 34055785, 2021).